MIR6732 (microRNA 6732)
Synonyms: hsa-mir-6732
Gene: MicroRNA gene on chromosome 1 (37,480,230 to 37,480,289, forward strand). Ensembl gene ENSG00000283724.
Homologues: Orthologues: chimpanzee MIR6732 (100% identical).